Y_RNA (Y RNA )
Gene: Miscellaneous RNA gene on chromosome 17 (59,260,748 to 59,260,846, forward strand). Ensembl gene ENSG00000207235.
Homologues: Orthologues: chimpanzee Y_RNA (100% identical), macaque Y_RNA (98% identical). Paralogues in human: Y_RNA (93% identical), Y_RNA (92% identical), Y_RNA (90% identical), Y_RNA (89% identical), RNY3 (88% identical), Y_RNA (88% identical), RNY3P1 (87% identical), Y_RNA (87% identical), Y_RNA (86% identical), RNY3P14 (85% identical), Y_RNA (85% identical), RNY3P11 (84% identical), and 97 more.